SGK3 (serum/glucocorticoid regulated kinase family member 3)
Diseases named in the same sentence as SGK3 in open-access papers (continued):
Sharing a sentence is not in itself a finding about the gene and the disease.
alopecia (1 paper, 2019). Hair loss usually from the scalp. "This study identifies the second hairless variant in the SGK3 gene in dogs and further highlights its role as a candidate gene for androgen-independent hair loss or alopecia in human." (PMID 30927068, 2019). "Our aim here was to identify the genetic cause and we describe the second hairless allele in SGK3, which represents a candidate gene for congenital human hair loss or alopecia." (PMID 30927068, 2019). "Canine studies with two spontaneous hairless alleles in SGK3 support the previous studies in mice and clearly demonstrate how defective SGK3 results in hair loss and alopecia." (PMID 30927068, 2019). "SGK3 represents an excellent candidate gene for human alopecia and should be screened for deleterious variants in human patients." (PMID 30927068, 2019).
bone cancer (1 paper, 2022). A primary or metastatic malignant neoplasm affecting the bone or articular cartilage. "Then, microglial activation with an increase in inflammatory cytokines in bone cancer pain rats was imitated using an LPS treatment in vitro; and miR-155-5p knockdown alleviated the augment of Tnf, Il1b, and Il6, which was possibly achieved by suppressing Sgk3 in vitro." (PMID 36143385, 2022).
cardiac hypertrophy (1 paper, 2022). "In addition, SGK3 could also participate in the development of cardiac hypertrophy and fibrosis by regulating the phosphorylation of GSK3β." (PMID 36531961, 2022).
chronic nasopharyngitis (1 paper, 2019). "The SGK3 expression level was significantly higher in NPC than in chronic nasopharyngitis tissue (p < 0.01), indicating that SGK3 expression is related to NPC carcinogenesis." (PMID 30108027, 2019). "The positive expression rates of SGK3 in NPC tissues and chronic nasopharyngitis tissues were 90.50% (38/42) and 11.10% (1/9), respectively." (PMID 30108027, 2019). "The SGK3 expression rate at different NPC stages and in chronic nasopharyngitis tissues was assessed according to the HSCORE." (PMID 30108027, 2019).
COVID-19 (1 paper, 2024). A disease caused by infection with severe acute respiratory syndrome coronavirus 2. "We subsequently identified two groups of specific DEPs: PPP2R5E, SGK3, CDC37, TSC2, and 20 other DEPs that were upregulated- or downregulated solely in the COVID-19 group, with no observed differences in the PQ group." (PMID 39301288, 2024).
developmental delays (1 paper, 2025). "We and others found Sgk3-KO mice exhibit mild developmental defects, including developmental delays during infancy and adolescence." (PMID 40767604, 2025). "Together with observations from our and other labs showing that Sgk3-KO mice maintain normal growth, development, and adult metabolic parameters, with only transient developmental delays, these findings suggest SGK3 as a promising therapeutic target with a favorable safety profile." (PMID 40767604, 2025).
epilepsy (1 paper, 2025). A brain disorder characterized by episodes of abnormally increased neuronal discharge resulting in transient episodes of sensory or motor neurological dysfunction, or psychic dysfunction. "Sgk3, Gsk3a, and Stk38, as well as other stress kinases that we found to be overexpressed in the brainstem, such as Map3k13, have been less well-studied in the context of epilepsy." (PMID 41511350, 2025).
gastric cancer (1 paper, 2023). A primary or metastatic malignant neoplasm involving the stomach. "In accordance with our data, INPP4B overexpression promoted SGK3 phosphorylation but did not influence p-AKT levels in AGS gastric cancer cells, while INPP4B reduction elevated AKT phosphorylation, but did not increase p-SGK3 levels in BGC823 gastric cancer cells." (PMID 36993823, 2023).
hair disorders (1 paper, 2019). "SGK3 has not been linked to human hair disorders, but remains as a strong candidate, particularly for congenital hypotrichosis and early hair loss with a monogenic defect." (PMID 30927068, 2019).
Hepatic steatosis (1 paper, 2019). Steatosis is a term used to denote lipid accumulation within hepatocytes. "Altogether, the results demonstrate that loss of SGK3 does not affect activated H1047R or E545K PIK3CA mutants induced hepatic steatosis in mice and lipogenesis in HCC cell lines." (PMID 30975125, 2019). "To determine whether SGK3 is required for activated PIK3CA mutant induced hepatic steatosis in vivo, we hydrodynamically transfected PIK3CA(H1047R) and PIK3CA(E545K) constructs, which we will refer here to as H1047R and E545K, into the Sgk3+/+ or Sgk3−/− mouse liver." (PMID 30975125, 2019).
influenza (1 paper, 2013). An acute viral infection of the respiratory tract, occurring in isolated cases, in epidemics, or in pandemics; it is caused by serologically different strains of viruses (influenzaviruses) designated A, B, and C, has a 3-day incubation period, and usually lasts for 3 to 10 days. "SGK3 belongs to the three member family of serum glucocorticoid kinases (SGK1, 2 and 3), and has been shown to regulate influenza vRNP nuclear export into the cytoplasm." (PMID 23805279, 2013).
ischemic stroke (1 paper, 2021). A stroke disorder caused by obstruction of blood flow to the brain, due to thrombotic (local blood clot formation) or embolic (due to a blood clot or other material traveling from another site) event. "Additionally, GSVA showed oligodendrocyte subcluster 9 was enriched in IL-6, complement, TNF-α pathway, and Kras signaling, suggesting that Sgk3 from oligodendrocytes may play an important role regulating oligodendrocyte viability and inflammatory responses during the acute stage of ischemic stroke." (PMID 33692998, 2021).
lung carcinoma (1 paper, 2022). "Experimental studies revealed that SGK3 was an oncogenic gene; however, TCGA analysis of several cancer data indicated SGK3 was downregulated compared with controls (including lung cancer, which was also confirmed in our prognosis and HPA analyses)." (PMID 35270630, 2022). "Thus, further experiments are necessary to confirm the expression levels and roles of SGK3 in CNT-related lung cancer." (PMID 35270630, 2022).
myocardial infarction (1 paper, 2022). Gross necrosis of the myocardium, as a result of interruption of the blood supply to the area, as in coronary thrombosis. "SGK3 (threonine-protein kinase 3) is a functional kinase we identified previously with the capacity to promote cardiomyocyte proliferation and cardiac repair after myocardial infarction." (PMID 36082129, 2022).
renal fibrosis (1 paper, 2024). A final common manifestation of a wide variety of chronic kidney diseases characterized by glomerulosclerosis and tubulointerstitial fibrosis. "SGK3/TOPK axis activation promotes CD206+ M2 macrophage polarization, causing renal fibrosis by mediating MMT generation." (PMID 39445007, 2024).
schizophrenia (1 paper, 2024). A major psychotic disorder characterized by abnormalities in the perception or expression of reality. "From our non-linear analysis, another two DMPs have been previously associated with schizophrenia, cg02488934 which is intergenic on chromosome 1, and cg14940705, which is annotated to SGK3." (PMID 39333502, 2024). "Of note, two DMPs (cg14940705, annotated to SGK3, and cg02488934, intergenic on chromosome 1) have been previously associated with schizophrenia." (PMID 39333502, 2024).
skin cancer (1 paper, 2025). "Because SGK3 appears to negatively regulate NOTCH1 levels, we depleted it in SCC022 skin cancer cells in which low levels of NOTCH1 promote tumorigenesis." (PMID 39663000, 2025). "We observed that SGK3 depletion resulted in elevated N1 TM, N1ICD levels, indicating that SGK3 contributes to the destabilization of NOTCH1 in skin cancer cells." (PMID 39663000, 2025). "Finally, SGK3 depletion leads to elevated NOTCH1 levels and elevated NOTCH1 target gene expression in skin cancer cells, suggesting that SGK3 might act as a negative regulator in contexts in which NOTCH1 is a tumor suppressor, such as during skin tumorigenesis." (PMID 39663000, 2025).
steatosis (1 paper, 2019). Increased lipid within the cytoplasm of cells. "Histological examination revealed that both H1047R and E545K mouse livers in Sgk3+/+ or Sgk3−/− genetic background showed the presence of numerous lipid-rich hepatocytes, leading to hepatic steatosis." (PMID 30975125, 2019).
cancer (30 papers, 2011 to 2025). A tumor composed of atypical neoplastic, often pleomorphic cells that invade other tissues. "Since SGK3 regulates cell cycle in cancers, we questioned the impact of SGK3 absence on preadipocyte cell cycle–associated functions and performed EdU labeling assays in vitro." (PMID 40767604, 2025). "Upregulation of Sgk3 activity has recently been linked to a number of human cancers; however, the precise mechanism of activation of Sgk3 is unknown." (PMID 34181950, 2021). "PIK3CA helical domain mutations are present in numerous cancer patients; thus, it has been hypothesized that targeting SGK3 may be an effective treatment option for tumors harboring PIK3CA helical domain mutations." (PMID 30975125, 2019). "Recently, Sgk3 has been shown to play a role in different cancers in an Akt-independent manner, highlighting the importance of Sgk3 as an effector downstream of PI3K signaling." (PMID 34181950, 2021). "Increasing studies have shown that SGK3 is dysregulated in cancer in an Akt-independent manner 33,34." (PMID 33613114, 2021). "Our data further suggest that combination of PDPK1 inhibitors with docetaxel enhances their anti‐cancer activity, possibly by targeting SGK3‐dependent resistance mechanisms." (PMID 32926495, 2020). "Further analyses revealed that PDPK1 mediates cancer cell survival predominantly via activation of serum/glucocorticoid‐regulated kinase 3 (SGK3)." (PMID 32926495, 2020). "For instance, it was reported that human cancers with PIK3CA mutations where AKT activity is deficient, SGK3 serves as the main PDPK1 effector to drive tumour cells survival." (PMID 32926495, 2020). "Recent work has revealed that the poorly studied AGC kinase family member, SGK3, promotes resistance to cancer therapies that target the Class 1 PI3K pathway, by substituting for loss of Akt kinase activity." (PMID 29150437, 2018). "Serum and glucocorticoid-regulated kinase 3 (SGK3) has been reported to play an important role in tumour progression, but its role in cancer stem cells (CSCs) remains obscure." (PMID 29940988, 2018). "On the other hand, recent studies uncovered an AKT-independent signalling pathway in PIK3CA mutant cancer cell with low AKT activation that involved PDK1-dependent activation of SGK3." (PMID 23408974, 2013). "Recent works indicate that SGK1 and SGK3 have an emerging role in cancer biology sustaining tumor growth in presence of PI3K/AKT inhibition and suggest that these genes could have an oncogenic function." (PMID 32848212, 2020). "Given the high sequence homology described for the three members of the SGK family we also analyzed the expression of SGK1 and SGK3 in normal and cancer-derived EOC cells and tested if their silencing could have any role in PT-sensitivity." (PMID 32848212, 2020). "Our data further suggest that combination of PDK1 inhibitors with selective PI3K inhibitors might enhance their anti-cancer activity, possibly by targeting SGK3-dependent resistance mechanisms." (PMID 31088502, 2019). "SGK3 plays an important role in the regulation of cancer cell proliferation and migration." (PMID 30108027, 2019). "Additional work is necessary to determine whether AKT2 and/or SGK3 are needed for tumor progression (that is, maintaining cancer growth once tumors are fully formed)." (PMID 30975125, 2019). "SGK3 has been found in others cancers as a carcinogenic gene." (PMID 30250399, 2018). "Previous work has shown that SGK3 is overexpressed in a variety of cancer cell lines and knockdown of SGK3 in these cells including in ZR‐75‐1 cells employed in this study has substantial impact on proliferation, results we have been able to confirm (RB, data not shown)." (PMID 27481935, 2016).
cancer (continued). "In addition, we identified genes associated with aggressive disease forms in CLL or other tumor entities, including serum- and glucocorticoid-inducible protein kinase 3 (SGK3), a regulator of the PI3K pathway and LIM domain only 7 (LMO7), which has been implicated in multiple cancer entities." (PMID 41214147, 2025). "It is likely that in addition to TSC2, SGK3 will phosphorylate a group of Akt substrates that could play important roles in driving metabolic, transcription and translational responses needed for the survival and proliferation of cancer cells." (PMID 27481935, 2016). "Moreover, it is emerging that PI3K could control other downstream targets in cancer cells, including serum/glucocorticoid-regulated kinase 3 (SGK3), in a manner which is independent from PIP3, but dependent on phosphatidylinositol 3-phosphate." (PMID 25871383, 2015). "Indeed, similar to Akt, SGK1 and SGK3 are involved in the pathogenesis of various types of cancers." (PMID 26573229, 2015). "In PTEN-intact cancer cells with low AKT activity, PI3K mainly utilizes AKT-independent signals via PDK1 and serum/glucocorticoid-regulated kinase-3 (SGK3)." (PMID 40427140, 2025). "SGKs, which consist of three isoforms, SGK1, SGK2, and SGK3, are critical mediators of AKT-independent signaling downstream of PDK1 and mTORC2 in cancer." (PMID 33960177, 2021). "SGK3-PROTAC1, at submicromolar concentrations, induced proteasomal-mediated degradation in several cancer cell lines." (PMID 34277564, 2021). "As a member of the SGK family, SGK3 activation and phosphorylation at Thr320 by phosphoinositide-dependent kinase-1 (PDK1) is considered an AKT-independent manner of signaling in cancer." (PMID 30108027, 2019). "Serum and glucocorticoid-regulated kinase 3 (SGK3), an AGC protein kinase family member, has been found to play a critical role in a variety of cancers." (PMID 29940988, 2018). "The reported role of Sgk3 in driving human cancers in the absence of Akt hyperactivation is then also reconcilable with this model and reinforces the potential value of Sgk3 as a therapeutic target either as a monotherapy or in combination with Akt inhibitors." (PMID 34181950, 2021). "In addition to identifying the mechanism of Sgk3 activation by PI3P, our findings open up potential therapeutic avenues in allosteric inhibitor development to target Sgk3 in cancer." (PMID 34181950, 2021). "Prolonged inhibition of class I PI3K promotes liver CSC expansion by augmenting SGK3-dependent β-catenin stabilisation, and effective inhibition of SGK3 signalling may be useful in eliminating liver CSCs and in PI3K pathway-targeted cancer therapies." (PMID 29940988, 2018). "Importantly, SGK3, that can be regulated through PDK1-dependent phosphorylation of residue Thr320 within its T-loop, has been identified as a key regulator of such PI3K/PDK1-dependent, Akt-independent signalling pathways in cancer." (PMID 31088502, 2019). "As many PIK3CA mutant cancers rely on effectors other than AKT, such as PDK1 and its substrate SGK3, phospho-AKT may not be an ideal pharmacodynamic biomarker for relevant PI3K inhibition." (PMID 27465249, 2016). "In numerous cancer cell lines, oncogenic PI3K activation has indeed recently been shown to be mediated not by AKT but by SGK3, another kinase that activates mTORC1, suggesting that AKT itself may be only one of several relevant targets for antileukemic interventions targeting the PI3K pathway." (PMID 24244612, 2013).
tumor (27 papers, 2014 to 2025). "ZMIZ2, a downstream target of SGK3, stabilizes β-catenin and promotes tumor progression, which has been linked to poor prognosis in estrogen receptor-positive breast cancer." (PMID 41502508, 2025). "Further analysis revealed that SGK3 was significantly upregulated in alpelisib-resistant cells, which was strongly associated with tumor stemness." (PMID 40303291, 2025). "Deficiency in INPP4B caused significant retardation of tumour growth in vivo, which was associated with reduction in SGK3 activation." (PMID 26573229, 2015). "Although some antitumor activity of BYL719 was observed in alpelisib-resistant cells, only the combination of BYL719 and SGK3 knockdown achieved the maximum inhibition of tumor growth." (PMID 40303291, 2025). "Particular evidence points to its role in cell growth, proliferation, migration, and apoptosis, and SGK3 is closely related to the (patho) physiological processes of tumor growth, hair growth, nervous system diseases, and cardiovascular diseases." (PMID 36531961, 2022). "In HCC, microRNA-144-3p acts as a tumor suppressor to suppresses tumor growth and angiogenesis by targeting SGK3 (Serum/Glucocorticoid Regulated Kinase Family Member 3)." (PMID 34634995, 2021). "Emerging evidence indicates that SGK3 is critical for tumor cells’ survival, proliferation, and invasion." (PMID 30975125, 2019). "There is also increasing evidence that a significant number of human tumours that are insensitive to class I PI3K inhibition display elevated levels of SGK3 and that this plays an important role in driving survival and proliferation." (PMID 25177796, 2014). "SGK3 knockdown resulted in a modest delay in tumor growth in shNC control xenografts." (PMID 40303291, 2025). "Moreover, the tumor spheres formation ability was greatly increased in SGK3 overexpressed MCF7 and T47D cells." (PMID 40303291, 2025). "Additionally, SGK3 can be used as a prognostic biomarker and a novel therapeutic target in tumor growth." (PMID 36531961, 2022). "This demonstrates that oncogenic Ras in contrast with growth factors is unable to activate Class 3 PI3K and emphasises that activation of SGK3 could contribute to Ras-driven tumour biology." (PMID 29150437, 2018). "Recently, SGK3 has been reported to be an important tumor-promoting gene." (PMID 30250399, 2018). "It would also be interesting to perform kinome‐wide mRNA profiling in a wide selection of tumour or patient‐derived cells before and after inhibitor exposure, so that drug resistance signatures in addition to SGK3 can be compared and contrasted as potential guides to inform targeted therapeutics." (PMID 27481935, 2016). "This demonstrated that myr-SGK3 effectively restored tumour growth." (PMID 26573229, 2015). "It will be important to identify physiological substrates for SGK3 and explore whether inhibiting Vps34 or SGK3 could be deployed as a therapeutic strategy to treat tumour cells displaying elevated SGK3 activity." (PMID 25177796, 2014). "Of note, the vast majority (15/20; 75%) of the HCC displaying increased SGK3 immunolabeling in the tumor part belonged to the group associated with poorer prognosis (HCCP), suggesting that SGK3 expression might contribute to HCC aggressiveness and survival, in agreement with a previous study." (PMID 30975125, 2019). "It has been shown that in tumor cells with minimal AKT activation, SGK3 conferred increased cell viability." (PMID 38674157, 2024). "The reduction of DKK1 activated the SGK3/FOXO3 pathway to accelerate cell migration and tumor metastasis." (PMID 33613114, 2021). "First, we determined SGK3 expression in E545K/c-Met, H1047R/c-Met, and sgPten/c-Met HCC tumor tissues." (PMID 30975125, 2019). "In colon cancer cells, INPP4B-mediated degradation of PTEN promoted tumour growth, proliferation and co-operatively enhanced AKT and SGK3 activation downstream of PI3K." (PMID 28082369, 2017).